PINCR (p53-induced noncoding RNA)
Synonyms: RP3-326I13.1
Gene: Long non-coding RNA gene on chromosome X (43,176,986 to 43,226,598, forward strand). Ensembl gene ENSG00000224294.
Diseases named in the same sentence as PINCR in open-access papers:
PINCR is named in the same sentence as 3 diseases in open-access papers, as found by Europe PMC text mining. Sharing a sentence is not in itself a finding about the gene and the disease. The quoted sentences say what the papers report.
colorectal cancer (2 papers, 2017 to 2024). A primary or metastatic malignant neoplasm that affects the colon or rectum. "PINCR has been shown to be critical for G1 cell cycle arrest and anti-apoptotic effects upon DNA damage in colorectal cancer cells, and PINCR loss-of-function results in increased sensitivity to doxorubicin and 5 fluorouracil (5-FU) treatment." (PMID 37782337, 2024).
cancer (1 paper, 2023). A tumor composed of atypical neoplastic, often pleomorphic cells that invade other tissues.
tumor (1 paper, 2017). "Future investigations on PINCR in normal cells and in an expanded panel of cell lines will enhance our understanding of its role in tumorigenesis and tumor progression." (PMID 28580901, 2017).